NT5DC4 (5'-nucleotidase domain containing 4)
Tractability: No criterion of Open Targets' tractability assessment is met for any kind of drug.
Gene: Protein-coding gene on chromosome 2 (112,721,020 to 112,742,879, forward strand). Ensembl gene ENSG00000144130.
Gene Ontology:
Molecular function: 5'-nucleotidase activity
Biological process: purine ribonucleotide catabolic process; dGMP metabolic process
Genetic constraint (gnomAD): Loss-of-function variants: 1 observed, 1.66 expected, observed/expected ratio (o/e) 0.6, 90% interval 0.19 to 1.81. That is too few expected variants to judge how well the gene tolerates losing a copy. Missense variants: 9 observed, 8.16 expected, observed/expected ratio (o/e) 1.1, 90% interval 0.66 to 1.78. Synonymous variants: 2 observed, 2.26 expected, observed/expected ratio (o/e) 0.89, 90% interval 0.33 to 1.85.
Homologues: Orthologues: chimpanzee NT5DC4 (89% identical), macaque NT5DC4 (78% identical), rabbit NT5DC4 (75% identical), pig NT5DC4 (65% identical), tropical clawed frog nt5dc4 (63% identical), zebrafish nt5c2l1 (55% identical), Drosophila melanogaster Nt5b (47% identical), Caenorhabditis elegans Y71H10B.1 (41% identical), Drosophila melanogaster Nt5c (21% identical). Paralogues in human: NT5C2 (59% identical), NT5DC3 (25% identical), NT5DC2 (24% identical), NT5DC1 (19% identical).
Diseases named in the same sentence as NT5DC4 in open-access papers:
NT5DC4 is named in the same sentence as 10 diseases in open-access papers, as found by Europe PMC text mining. Sharing a sentence is not in itself a finding about the gene and the disease. The quoted sentences say what the papers report.
cancer (2 papers, 2023). A tumor composed of atypical neoplastic, often pleomorphic cells that invade other tissues. "NT5DC1 expression correlated with patient sex, NT5DC3 expression was significantly associated with cancer grade, and NT5DC4 expression was associated with tumor diameter." (PMID 37576396, 2023).
NT5DC4 also shares sentences with these, for which no sentence is quoted: acute leukemia (1 paper); astrocytoma (1); breast carcinoma (1); colorectal carcinoma (1); glioblastoma (1); hepatocellular carcinoma (1); leiomyosarcoma (1); lung carcinoma (1); tumor (1).